TOX (thymocyte selection associated high mobility group box)
Diseases named in the same sentence as TOX in open-access papers (continued):
Sharing a sentence is not in itself a finding about the gene and the disease.
tumor (continued). "It is worth noting that VEGFR2 knocking out CD8+ T cells can down-regulate TOX expression and reactivate tumor-specific CD8+ T cells, confirming that targeting the VEGF/VEGFR2 pathway can reverse T cell depletion and enhance the antitumor effect of ICIs." (PMID 34477165, 2021). "Previous studies have shown that TOX is a critical regulator of tumor-specific T cell differentiation and an initiator of the exhausted CD8+ T cell-specific epigenetic program." (PMID 33897695, 2021). "The tumor-suppressive function of TOX on tumorigenesis was confirmed in mice using flank tumors to model tumorigenesis and tail vein injection to model metastasis." (PMID 33897695, 2021). "The TOX-RUNX3 pathway inhibits the expression of RUNX3 when TOX is highly expressed, thereby affecting the tumor suppression function." (PMID 33743809, 2021). "Overall, these findings indicate that TOX serves as a supporting factor for the tumor antigen-specific Tc to persist in the tumor environment and a self-protection mechanism from overstimulation and dying." (PMID 32823814, 2020). "We further compared the tumor infiltration level in LUAD with different somatic copy number alterations (SCNA) of TOX." (PMID 32700817, 2020). "The expression level of TOX on tumor infiltrating CD8+ T cells was negatively correlated with anti-PD1 response rates in melanoma and NSCLC patients." (PMID 32793604, 2020). "Here, we acquired and analyzed extensive tumor samples from several large databases and found that TOX expression level is correlated with prognosis in multiple types of tumor, particularly LUAD." (PMID 32700817, 2020). "TOX is specifically required for T cell differentiation in an environment of chronic antigen stimulation (e.g., tumours and chronic infections)." (PMID 32047816, 2020). "TOX is a newly discovered gene, and three consecutive articles published in Nature recently introduced the role of the TOX gene in tumour immunotherapy." (PMID 32047816, 2020). "TOX and TOX2 deficient CAR+ TILs can prevent tumor growth and prolong survival of tumor-bearing mice." (PMID 32117960, 2020). "We found that TOX is a potential prognosis‐related biomarker in LUAD and provided novel direction to understand the interactions between TOX expression, tumor infiltration, and T cells exhaustion." (PMID 32700817, 2020). "Based on the IVY GBM database, the analysis of RNA sequencing data revealed the high expression of TOX in cellular tumour, leading edge, and infiltrating tumour." (PMID 32762688, 2020). "Recently, TOX was revealed its crucial role in tumor‐specific T cell differentiation and CD8+ T cell exhaustion, highlighting a potential biomarker for response prediction or enhancement of cancer immunotherapy." (PMID 32700817, 2020). "The TI lymphocytes derived from tumor tissue of patients with NSCLC were transfected with TOX siRNA." (PMID 32111241, 2020). "In preclinical models and patient tumor biopsies, TOX expression is up‐regulated in early Texh cells, where it establishes epigenetic signatures required for cell persistence." (PMID 32272497, 2020). "In order to preliminarily evaluate the role of TOX in tumorigenesis, we analyzed the different expression levels of TOX between tumor and adjacent normal tissues in all TCGA tumors." (PMID 32700817, 2020). "In this work, we investigated the expression level of TOX and its prognostic potential in various types of tumor using several databases comprised a large number of tumor and normal samples." (PMID 32700817, 2020). "Aberrant expression of TOX plays a central role in malignant survival, proliferation, and tumor formation in CTCL." (PMID 31676945, 2020). "Thymocyte selection-associated high mobility group box gene (TOX) was reported as a positive regulator of PD1, TIM3, TIGIT, and CTLA4 expression in the tumor infiltrating CD8+ T cells, regulating CD8+ T cell exhaustion." (PMID 32793604, 2020).
tumor (continued). "Among these immune checkpoints, it is worth noting that a molecule called TOX is a newly discovered gene, and three consecutive articles published in Nature recently introduced the role of the TOX gene in tumour immunotherapy." (PMID 32047816, 2020). "Knocking down TOX in tumor-specific CD8+ T cells promoted the anti-tumor effects of these T cells, exhibiting the synergetic role of anti-PD-1therapy." (PMID 32117960, 2020). "Using the scRNA-seq data generated from human tumor samples, we also independently demonstrated that TOX promotes CD8+ T cell exhaustion in human cancer." (PMID 32111241, 2020). "In the presence of tumor antigen stimulation, TOX expression is increased in CD8+ T cells in HCC tissue, and this TOX upregulation is associated with the T cell dysfunction of CD8+ TILs." (PMID 33379384, 2020). "When antigens in the environment cannot be removed, TOX regulates the balance between T cell-mediated virus/tumor control and immune response, thereby preventing T cell death and immunopathology due to excessive activation." (PMID 33299644, 2020). "Next, to test if TOX expression varies with tumor burden, TOX mRNA levels were plotted according to lesional morphological types, such as patches, plaques, and tumors." (PMID 24947046, 2014). "This better tumor growth control was associated with increased infiltration of PD-1High CD8+ T cells, expressing elevated levels of exhaustion markers and transcription factors such as TOX." (PMID 41668741, 2026). "Therefore, more TCF-1 + Teffs and fewer TOX + Teffs in tumors mediate the tumor control induced by ITPP, αCTLA-4 and αPD-1." (PMID 40594309, 2025). "Indeed, TOX-expressing CD8+ TILs from E0771 tumours grown in DR-fed mice exhibited increased IFNγ production and elevated TCF1 levels, a marker of cell stemness." (PMID 41366157, 2025). "T cell exhaustion, a dysfunctional state marked by TOX-driven transcriptional reprogramming and sustained expression of inhibitory receptors (e.g., LAG-3, CTLA-4), is a hallmark of chronic viral infections and tumor microenvironments." (PMID 40830893, 2025). "Furthermore, there were more stem-like TCF-1+CD8+T cells and less exhausted TOX+CD8+ T cells in B7-H4-KO tumor tissues." (PMID 40341398, 2025). "Importantly, Jurkat cells with TOX knockdown or TIM3 overexpression slowed the tumor growth in nude mice." (PMID 39080376, 2024). "However, TOX has been identified as a crucial factor in tumor-specific T-cell differentiation and CD8+ T-cell exhaustion, linking it to the prognosis of cancers or response prediction, or the enhancement of cancer immunotherapy." (PMID 39080376, 2024). "Targeting TOX or TIM3 overexpression slowed Jurkat-tumor growth in nude mice." (PMID 39080376, 2024). "Though TOX was a central regulator of T cell exhaustion, and ablating it prevented differentiation towards exhaustion, TOX prevented overstimulation of T cells and activation-induced cell death, thereby ensuring persistent T cells in tumours." (PMID 38581063, 2024). "Furthermore, KO of TOX2 in addition to shRNA downregulation of TOX in CAR-T cells (Tox DKO T cells) further enhanced tumour control." (PMID 39399500, 2024). "Comparing IL-4 expression in thymocyte selection-associated HMG BOX (TOX)+ CD4+ T-cells between plaque and tumor lesions, a significant increase in IL-4 and TOX expression was observed in the tumor stage, with a positive correlation between the levels of TOX and IL-4 expression." (PMID 38397043, 2024). "Treatment with anti-PD-L1 + mIgG2a anti-TIGIT antibodies increased the proportion of gp70-specific CD8+ T cells in the tumour and drove those cells to downregulate TOX while upregulating TCF1, consistent with a shift from exhausted effector cells towards a more memory-like state." (PMID 38418879, 2024). "CTLs with high expression of TOX have been reported in diverse tumor models in humans and mice." (PMID 36969216, 2023).
tumor (continued). "Here, we report a novel delivery system of FEGCG/FPEI@siTOX composed of fluorinated EGCG (FEGCG) and fluorinated polyethyleneimine (FPEI) for delivery of small interfering RNA anti-TOX (thymus high mobility group box protein, TOX) to treat tumor and metastasis." (PMID 37957632, 2023). "Because tumor-specific CD8+ TILs are chronically stimulated at the tumor site, we hypothesized that TOX, LMCD1, and AFAP1L2 might be induced upon chronic stimulation." (PMID 37388918, 2023). "The necessity of TOX for CD4 lineage development suggests that its abnormal expression may lead to clonal proliferation of malignant T tumor cells." (PMID 36969216, 2023). "Interestingly, CAR TILs deficient in both TOX and TOX2 showed increased effector functions and prolonged survival of tumor-bearing mice, and their exhausted features were obviously attenuated." (PMID 36761757, 2023). "Deletion of TOX in tumor-specific T lymphocytes (TST) cancels the exhaustive procedure." (PMID 36969216, 2023). "Notably, sCRC displayed a significantly elevated abundance of TOX+ cells both within the tumor microenvironment and in the adjacent tumor-free mucosa when compared to CAC." (PMID 37835436, 2023). "However, it was found that CAC exhibited a significantly enriched presence of TIGIT (p = 0.011) and TOX (p < 0.0001) in comparison to the corresponding tumor-free mucosa." (PMID 37835436, 2023). "As a key upstream regulatory factor affecting CTL exhaustion, TOX may be a potential target for tumor therapy." (PMID 36969216, 2023). "TOX has been found to regulate innate immunity and the tumor microenvironment." (PMID 35519421, 2022). "However, the increase in TOX expression comparing patch/plaque and tumour lesions along with changes in the marker’s expression in sequential biopsies of progressed cases warrants a comment." (PMID 35885488, 2022). "The reason why TOX was not an independent predictor was that TOX expression was significantly associated with tumor stage on which the DFS was tightly related." (PMID 36434543, 2022). "TOX expression was elevated in tumor tissues compared to normal adjacent tissues." (PMID 36434543, 2022). "Moreover, a stage-related increase in TOX levels was found analysing tumour (high expression) plaque (intermediate expression) and patch lesions (low expression)." (PMID 35885488, 2022). "Variations in TOX expression were observed across tumor tissues." (PMID 36434543, 2022). "We found that TOX was not only expressed in CD8 T cells but also tumor cells." (PMID 36434543, 2022). "Indeed, VEGFA can induce the activation of the master regulator of T cell exhaustion, TOX, as well as the expression of the PD-1 checkpoint in tumor-reactive, CD8+ T cells." (PMID 35577211, 2022). "Here, we observed that low levels of immune-inhibitory factors, such as TOX and Foxp3, as well as high numbers of infiltrated lymphocytes in tumor tissues and high baseline levels of inflammatory cytokines may predict a clinical benefit for auto-TIL treatment." (PMID 35727633, 2022). "However, general principles of CD8+ T cell exhaustion/dysfunction seem to be conserved between virus-specific and tumor-specific CD8+ T cells which is best reflected by the common master regulator TOX." (PMID 33801203, 2021). "In conclusion, our in vitro and in vivo data indicate that TOX acts as a CRC tumor suppressor to inhibit tumorigenesis and metastasis, and rapamycin or combined with PD1 inhibition may be a promising treatment for CRC." (PMID 33897695, 2021). "Strikingly, even in a tumor lesion where the percentage of TOX+ cells was high at the basal level (40%), culturing with IL-4 still increased the expression of TOX and the percentage of TOX+ cells (67.2%)." (PMID 34220814, 2021). "In addition, TOX expression in tumor‐infiltrating T cells can be used to stratify patients during antitumor therapy, including anti‐PD‐1 immunotherapy." (PMID 33626234, 2021). "TOX is highly expressed in dysfunctional tumor-specific CD8 T cells." (PMID 33490273, 2021).
tumor (continued). "We observed that IL-4 promotes a positive feedback loop by i) promoting NLRP3 nuclear localization, ii) boosting TOX expression and TOX+ cell proliferation, which upregulates IL-4, and iii) favoring a dominance of Th2 responses in advanced stages of the disease (tumor)." (PMID 34220814, 2021). "Expression of TWIST1 and TOX is frequently increased in tumor T cells from CTCL patients." (PMID 33941102, 2021). "Up-regulating TOX may inhibit the expression of tumor suppressor genes, which may be a reason for tumor maintenance." (PMID 33743809, 2021). "In addition, TOX knockdown in TI CD8+ T cells from human tumor reduced the number of cells expressing PD-1, TIM-3, TIGIT, and CTLA-4." (PMID 32111241, 2020). "TOX was highly expressed in leading edge regions of tumours." (PMID 32762688, 2020). "On the other hand, signatures common to all tumours, such as TOX gene expression or the expression of certain genes identifying actively-proliferating lymphocytes, could be used for the diagnosis and monitoring of treatment." (PMID 32751918, 2020). "We next evaluated the intra-tumour distribution of TOX in GBM samples." (PMID 32762688, 2020). "Interestingly, KIRP with low expression level of TOX has better prognosis while the TOX expression of tumor tissues is also lower than normal." (PMID 32700817, 2020). "TOX is already known to play an important role in the development of several homeostatic leukocyte populations, but it is an intriguing exhaustion marker in cancer context given its pleiotropic effects within tumor Texh cells." (PMID 32272497, 2020). "Previous studies have indicated the crucial role of TOX in tumor immunity." (PMID 32700817, 2020). "This may explain why TOX knockdown will lead to less cell viability and colony-forming ability in vitro and reduce tumor growth in vivo." (PMID 31676945, 2020). "This study comprehensively analyzed TOX expression and its prognostic value in various kinds of cancers using multiple databases including Tumor Immune Estimation Resource (TIMER), PrognoScan, Gene Expression Profiling Interactive Analysis 2 (GEPIA2), and Kaplan‐Meier plotter." (PMID 32700817, 2020). "Additionally, TOX expression in the TI T cells can be used for patient stratification during anti-tumor treatments, including anti-PD-1 immunotherapy." (PMID 32111241, 2020). "Also, CAR-TILs with double deficiency of TOX and TOX2 were more effective in mediating tumor regression than single knockouts or WT." (PMID 32823814, 2020). "Tumor-infiltrating CD8+ T cells also showed decreased abundance of TOX, programmed cell death protein-1 (PD-1), T cell immunoglobulin, mucin domain-3 (TIM-3), and killer cell lectin-like receptor subfamily G member 1 (KLRG1), indicating the cells remained functional effector cells." (PMID 33353953, 2020). "TOX was the only transcription factor (TF) predicted in both tumor types." (PMID 32111241, 2020). "In addition, HDAC8 expression was positively correlated with the genes encoding T‐cell exhaustion‐related genes, including TOX and DDIT3, and negatively correlated with the transcript genes encoding T‐cell activation‐related genes, such as TBX21, in multiple tumor types." (PMID 40013761, 2025). "Furthermore, TOX plays a critical role in the differentiation of tumor-specific T cells." (PMID 39845086, 2024). "Using our protocol, CAR T cells, regardless of which ICD was included, that were repeatedly stimulated with tumor cells secreted significantly lower levels of proinflammatory cytokines and upregulated the expression of IL-10 and the exhaustion-related transcription factor TOX." (PMID 37932456, 2023). "Tumour antigen-reactive TILs contained features of mouse TEX and were enriched for gene signatures associated with tissue residency (CD103, HOBIT), effector function (GZMB, IFNG), negative feedback (HAVCR2, ENDTP1 (CD39)), and transcriptional control of exhaustion (TOX, BLIMP1)." (PMID 37386922, 2023).
tumor (continued). "Thus, the expression levels of TOX maybe reflect the function of CD8 T cell in the tumor microenvironment and thus can predict the prognosis of cancer patients." (PMID 36434543, 2022). "In both MC38 and CT26 tumors, the majority of CD8 T cells retained within the tumor for at least 24 h (Kaede Red+) expressed high levels of PD-1, in contrast to those newly entering (Kaede Green+), and furthermore, only these Kaede Red+ cells contained a clear PD-1+ TOX+ population." (PMID 35472220, 2022). "Unfortunately, TOX is not considered as a tumor cell-specific marker, but TOX expression can be an adjunctive diagnostic marker, similar to loss of pan T-cell markers, and might be added in the diagnostic algorithm for early MF." (PMID 34574062, 2021). "In addition, we found that the expression levels of T-cell exhaustion-related genes including CD40, GRB2, MKI67, NFATC3, PRDM1, TCF7, and TGFB1 were significantly higher, while those of CXCR5 and TOX were significantly lower after tumor recurrence (all p < 0.05)." (PMID 34305618, 2021). "Studies in tumour-bearing mice have demonstrated that the exhaustion pathway is established early during tumourigenesis, has an epigenetic signature distinct from the effector pathway, and is established and maintained by the action of the transcription factor and epigenetic modifier TOX." (PMID 32824734, 2020). "The correlation between TOX protein expression and severity of intra-tumoral T cell exhaustion was evaluated by flow cytometric analysis of TI lymphocytes isolated from human primary tumor specimens from patients with NSCLC or HNSCC who underwent surgical resection at the Severance Hospital." (PMID 32111241, 2020). "Additionally, we observed that the frequency of TI CD8+ T cells that secrete effector cytokines (IFN-γ and TNF-α) significantly increased upon TOX knockdown, suggesting that the anti-tumor function of TI CD8+ T cells could be restored upon TOX knockdown." (PMID 32111241, 2020). "Finally, TOX had a negative association with the infiltration of several immune cell types in the tumour microenvironment." (PMID 32762688, 2020). "Moreover, knockdown of TOX was associated with increase in RUNX3 expression levels, indicating that TOX may act to decrease RUNX3′s tumor suppressor functions in SS." (PMID 31139323, 2019). "One study found that in tumor-infiltrating CAR-T cells, there were CD8+ CAR+ PD-1+ TIM3+ cells, and exhaustion-related transcriptional factor TOX was highly expressed." (PMID 41502492, 2026). "LOY tumor cells displayed more dysfunctional and exhausted CD8+ T cells (i.e., higher levels of TOX expression), suggesting that LOY in cancer cells alters T cell function in the surrounding tumor microenvironment." (PMID 41580387, 2026). "While CD8+ T cells are critical for anti-tumor immunity, they often become dysfunctional in the TME and express the exhaustion markers LAG3 and TOX." (PMID 41194931, 2025). "CD8+ T cells that exhibited high expression levels of exhaustion gene (HAVCR2, ENTPD1, LAG3, PDCD1, CXCL13, TOX, and GZMB) in the primary tumor were extracted and clustered." (PMID 40364834, 2025). "The accumulation of Tex cells in tumours is driven by TOX and is reinforced through epigenetic programming, ultimately limiting the ability of CD8+ T cells to control tumour growth." (PMID 41366157, 2025). "Intriguingly, compared with single KOs, the double KO of TOX and TOX2 achieved superior tumor control." (PMID 40693464, 2025). "These nominated clusters upregulated key marker genes of activation, dysfunction, and differentiation that have been used to identify tumor specificity, such as CXCL13, TIGIT, PDCD1 (PD1), ENTPD1 (CD39), TOX, HAVCR2 (TIM-3), and LAG3." (PMID 40848148, 2025). "Differential expression analysis at the single-cell level revealed that TOX expression was significantly elevated in both CD8+ effector and tissue-resident T cells in tumor and adjacent normal tissues compared to healthy tissues." (PMID 40698080, 2025).